TNF (tumor necrosis factor)
Diseases named in the same sentence as TNF in open-access papers (continued):
Sharing a sentence is not in itself a finding about the gene and the disease.
psoriasis (continued). "This is of particular importance for patients with IBD and psoriasis and the anti-TNF-α infliximab, certolizumab, and golimumab agents, which were underrepresented in the current review." (PMID 35625771, 2022). "Adalimumab (TNF inhibitor), etanercept (TNF inhibitor), and ustekinumab (IL-12/23 inhibitor) are approved for both adult and pediatric psoriasis." (PMID 36226155, 2022). "Despite the inhibition of cytokine signaling, including TNF-α, as one of the main bioactivities attributed to HTs, few studies have been carried out to elucidate their potential role in psoriasis." (PMID 36364420, 2022). "Previous studies have shown that the TNF-α and IL-23/IL-17A axis is the main driver of psoriasis, and the interaction between IL-17A and keratinocytes is a key issue in developing psoriasis." (PMID 36590975, 2022). "The mechanism of action for biologics used in psoriasis treatment is targeting different cytokines such as tumor necrosis factor (TNF)-α, IL-12/23, IL-17, and IL-23." (PMID 36579586, 2022). "A previous study showed that Egr-1 is significantly upregulated in the skin lesions of psoriasis patients and promotes TNF-α production." (PMID 35693817, 2022). "The proinflammatory cytokines, generated by both immune cells and keratinocytes, such as TNF-α, IL-17A and IL-23, induce and aggravate the development of psoriasis." (PMID 35938153, 2022). "In patients with refractory psoriasis, the combination of acitretin and the TNF-α monoclonal antibody like etanercept has achieved a good result." (PMID 35814239, 2022). "It is now accepted that TNF-α plays a critical role in the pathogeneses of certain autoimmune diseases, including RA and psoriasis." (PMID 35884790, 2022). "Anti-TNF-α therapy is effective and results in rapid clinical responses in psoriasis patients, making these drugs one of the first-line therapies." (PMID 35330186, 2022). "The pathogenesis of metabolic syndrome in patients with psoriasis is believed to have a connection with an increase in adipocytokines such as tumor necrosis factor-α (TNF-α) and adiponectin." (PMID 35492738, 2022). "The IL-17 signaling pathway and TNF signaling pathway are essential in pathological processes of psoriasis." (PMID 35669784, 2022). "Upregulated inflammatory cytokines in the skin and peripheral blood of psoriasis patients, such as interferons, TNF-a, IL-1, IL-6 and IL-10, had an effect on erythropoiesis, leading to the enhanced RDW." (PMID 35213665, 2022). "We found that psoriasis-related cytokines, namely IL-17, IL-22, IL-1β, and TNF-α, reduced CAV-1 expression in human keratinocytes." (PMID 36532050, 2022). "These authors mentioned also other cases where the administration of anti-TNFα agents was successful, among others in AD, so they postulate common pathogenesis of psoriasis and AD in terms of TNFα participation." (PMID 36226313, 2022). "IL-17, alone or synergistically with TNF-α acting on keratinocytes, results in the transcription of many psoriasis-related genes, including CCL20, CXCL1, -2, -3, and -8 chemokines." (PMID 35216231, 2022). "The mRNA levels of psoriasis‐related inflammatory factors such as TNF‐α, IL‐23, IL‐17A, IL‐1β and IL‐6 were measured by RT‐PCR." (PMID 35023281, 2022). "Over the past two decades, inflammatory circuit triggered by various cytokines (e.g., IFN-γ, TNF-α, and IL-1β) have been found to play an important role in regulating the development and progression of psoriasis." (PMID 36618400, 2022). "The use of treatments in patients with psoriasis reduces the level of TNF-α in psoriatic lesions which allows melanocytes to produce pigment." (PMID 36613652, 2022). "The level of TNFα was elevated in moderate and severe psoriasis (PASI > 10 and BSA > 16) compared with mild forms of the disease." (PMID 35886575, 2022). "At present, it is proven that TNF-α plays an important role in the pathogenesis of psoriasis, and because of that, it has become the first target of modern therapies." (PMID 35563587, 2022).
psoriasis (continued). "In a recent meta-analysis including patients with IBD treated with anti-TNF-α agents, the pooled incidence of any dermatological reaction was 19% (95% confidence interval (CI) 15–24), with psoriasis or psoriasiform rash being the most common." (PMID 35625771, 2022). "To evaluate the potential pharmacological effect of PUN on psoriasis, we made use of imiquimod (IMQ)-induced psoriasis-like mice model and tumor necrosis factor α (TNF-α) and IL-17A-stimulated HaCaT cells." (PMID 35153790, 2022). "Although the underlying molecular mechanism is still not fully comprehended, these data highlight the potential relevance of the anti‐psoriasis therapeutics based on TNFα or IL‐17 antagonists." (PMID 36245291, 2022). "Cytokines such as tumor necrosis factor-alpha (TNFα) and interleukin 6 (IL-6) are directly involved in the pathology of psoriasis and are targets of some highly effective therapies." (PMID 35806402, 2022). "The final analysis (n=82) included 67 individuals with psoriasis receiving therapeutic immunosuppression, including methotrexate (n=14), TNF inhibitors (n=19), IL-17 inhibitors (n=14), IL-23 inhibitors (n=20), and 15 healthy volunteers (the control group)." (PMID 34778846, 2022). "Dysbiosis and gut-skin axis participation are common features of many inflammatory diseases like IBD or psoriasis, in the pathogenesis of which TNF plays an important role." (PMID 36704107, 2022). "Decreased CAV-1 expression in monocytes was reversed when patients were treated with anti-TNF-α antibodies, suggesting that psoriasis-related inflammatory cytokines also reduce CAV-1 expression in monocytes." (PMID 36532050, 2022). "The combination of cytokines (TNFα and IL-17A) both being important targets in psoriasis development were utilized in vitro to activate and promote keratinocytes proliferation and inflammatory responses while examining the intervention with the test compounds." (PMID 36741386, 2022). "Immunohistochemistry was performed to confirm the counts of Ki67+, CD3+, IL-6+, and TNF-α+ cells in psoriasis skin lesions." (PMID 35359454, 2022). "TNF-α is thought to play a key role in the pathogenesis of psoriasis, and anti-TNF-α therapy has proven to be effective." (PMID 35351863, 2022). "In last few years, advances in understanding molecular and cellular pathways have identified tumor necrosis factor-α (TNF-α), interleukin-17 (IL-17), IL-23, IL-22 as major contributors in psoriasis pathogenesis." (PMID 35265634, 2022). "We compared the CNVs derived from the different clinical phenotypes of psoriasis (N = 39) with anti-TNF-induced PPP (N = 6)." (PMID 36143237, 2022). "At present, traditional systemic medications methotrexate, acitretin, cyclosporine and biologics anti‐TNFα, anti‐IL‐12/23, anti‐IL‐17 are the main treatment options for psoriasis." (PMID 35174638, 2022). "There is at present no strong, definite evidence for a significant beneficial effect of anti-TNF-α biologics on endothelial function in psoriasis, although some promising data do exist." (PMID 35755028, 2022). "It has been reported that keratinocytes in psoriasis patients are under stress and can secrete TNF-α and IL-6 to activate dendritic cells (DCs) to promote the progression of psoriasis." (PMID 36618400, 2022). "While therapies targeting tumor necrosis factor (TNF)-α, IL-23 and IL-17 have been proven effective in psoriasis, topical treatment remains the method of choice in most cases." (PMID 35886201, 2022). "In this model, immunostaining showed that antigen-presenting cells were the predominant source of TNF-α, and neutralizing TNF-α resulted in decreased psoriasis development and a significant reduction in the number of T cells in the graft." (PMID 35884790, 2022). "Previous studies have shown that the infiltration of M1-Mø greatly elevates the expression of inflammatory cytokines such as interleukins and TNF-α, which triggers psoriasis by stimulating the proliferation and inflammation of keratinocytes." (PMID 36467042, 2022).
psoriasis (continued). "Then, we verified the results in psoriatic lesions and a psoriasis model in vitro by stimulating keratinocytes with IL-17A, IL-22, IL-1α, oncostatin M, and TNF-α (M5)." (PMID 35586566, 2022). "Infliximab is an IgG1 murine–human antibody which has the ability to bind with high affinity and specificity to TNF-alpha, leading to important neutralizing and inhibitory activities which interfere with the inflammatory cascade in psoriasis." (PMID 35741329, 2022). "Emerging evidence from clinical trials has shown that monoclonal antibodies to IL-23, IL-17, and TNF are effective in treating patients with psoriasis, atopic dermatitis, pyoderma, rosacea, pemphigus, and scleroderma systemic." (PMID 35805534, 2022). "Although studies have been limited, recent research has proposed a difference in TNF-α, IL-17, IL-22 expressions in pediatric psoriasis patients compared with those in adult psoriasis patients." (PMID 36232430, 2022). "Dominant cytokine profiles of IFN-γ and TNF-α were overlapped with psoriasis lesional skin and atherosclerotic plaque which induced the inflammatory reaction in the endothelium." (PMID 35457278, 2022). "IFX, a recombinant humanized monoclonal antibody against TNF-α, is now approved for use in several immune-mediated disorders, including psoriasis, RA, IBD, ankylosing spondylitis, and IVIG resistant KD." (PMID 35223745, 2022). "Anti-TNF-a therapy in children is safe, adverse events were mostly mild, and complications such as the development of an adverse psoriasis were observed in approximately 13% of patients." (PMID 36304532, 2022). "Other proinflammatory cytokines, including IFN-γ, TNF-α, IL-1β, IL-6, IL-22, IL-26, IL-29, or IL-36, have also been reported to play important roles in the development of psoriasis." (PMID 35313642, 2022). "Psoriasis is a chronic inflammatory dermatologic disease mediated by cytokines, including tumor necrosis factor‐α (TNFα), interleukin‐17, and interleukin‐23." (PMID 35799412, 2022). "Etanercept, the first TNF‐α inhibitor to treat psoriasis, was approved by the U.S. Food and Drug Administration." (PMID 35281792, 2022). "Among biologic therapies, TNF alpha inhibitors such as adalimumab and IL-17 inhibitors such as brodalumab were found to have a positive effect in patients with HS and psoriasis." (PMID 36532043, 2022). "Since that IL-17A and TNF-α are the key inflammatory cytokines in the pathogenesis of psoriasis, we used IL-17A and TNF-α to stimulate HaCaT cells and conducted an inflammatory psoriatic in vitro model." (PMID 35153790, 2022). "Biological anti-TNF-α therapies are routine medications used in patients with rheumatoid and psoriatic arthritis, psoriasis, ankylosing spondylitis or Crohn’s disease." (PMID 36428528, 2022). "M1 macrophages are considered to contribute to the development of psoriasis especially in early-phase psoriasis, by producing TNF-α." (PMID 35837394, 2022). "The serum levels of pro-inflammatory cytokines such as IFN-7, TNF-α, IL-1β, IL-6, IL-8, and IL-17 significantly decreased in patients with psoriasis after a three-month administration of vitamin D supplement." (PMID 36558443, 2022). "During the early onset of psoriasis, DCs release TNF-α along with other cytokines, such as IL-23, to signal for the assembling of CD4+ and CD8+ T cells." (PMID 35203707, 2022). "Previous studies have shown that inflammatory adipocytokines such as IL-6 and TNF-α formed in visceral adipose tissue are key cytokines in the pathogenesis of psoriasis, so it is believed that psoriasis is related to obesity." (PMID 36119103, 2022). "Further evaluation using a psoriasis SE model will be necessary to exclude the possibility of a deleterious effect of anti-TNFα treatment to the epidermis." (PMID 35742957, 2022). "Due to increased levels of TNF-α and IL-12 in psoriatic lesions, psoriasis is defined as Th1-mediated disease." (PMID 35313642, 2022).
psoriasis (continued). "In patients with congestive heart failure, the European Guidelines for the Treatment of Psoriasis Vulgaris recommend the use of anti-IL-23 molecules instead of anti-TNF therapy." (PMID 35563587, 2022). "In psoriasis, macrophages acquire a pro-inflammatory phenotype and produce cytokines such as IL-23, TNF-α, and IL-1β." (PMID 36591241, 2022). "Compound 1 also clearly inhibited the phosphorylation of STAT3, which regulates the expression of cytokines, and CCL20 chemokines in TNF-α /IL-17A/ IFN-γ induced the psoriasis condition." (PMID 36015080, 2022). "Inflammatory cytokines, mainly tumor necrosis factor α (TNF‐α); interleukin (IL) 1, IL‐6, IL‐8, and IL‐36; and T helper 17‐related cytokines (IL‐17, IL‐22, and IL‐23) are involved in the pathogenesis of psoriasis." (PMID 36151864, 2022). "In vivo studies revealed that tumor necrosis factor (TNF)-α induces IL-24 to drive psoriasis-like skin inflammation in mice." (PMID 35054813, 2022). "Many cases of paradoxical skin reactions—especially psoriasis—secondary to the use of TNF α inhibitors have already been reported, as well as other immune-mediated inflammatory diseases." (PMID 35203664, 2022). "Collectively, these findings suggest that TNF-α is, indeed, a good candidate with which to establish a specific treatment regime for psoriasis." (PMID 35203707, 2022). "In a randomized clinical trial, the effects of ustekinumab (IL-12/IL-23 inhibitor), etanercept (TNF-α inhibitor), or cyclosporine were compared regarding the heart function and oxidative stress in patients with psoriasis." (PMID 35313642, 2022). "Biologic agents, specifically anti-TNF alpha, have revolutionized the therapeutic armamentarium of several immune-mediated diseases such as psoriasis, atopic dermatitis, and HS." (PMID 36358228, 2022). "Still, lymphocytes also produce TNFα, a cytokine the higher level of which is observed in the synovial fluid of psoriasis patients and whose inhibitors alleviate the course of psoriatic arthritis." (PMID 36292991, 2022). "Biologics targeting IL-17A and TNF-α have demonstrated greater effectiveness than traditional strategies in treating psoriasis for decades." (PMID 35669784, 2022). "These cells are a significant source of proinflammatory cytokines, especially tumor necrosis factor α (TNF-α), and interleukin-6, which lead to the progression of psoriasis." (PMID 35335900, 2022). "In the pathogenesis of psoriasis, IL-23-mediated activation of the Th17 pathway is regarded as the central inflammatory cascade, and biologics, such as TNF-α inhibitors, IL-23 inhibitors, and IL-17 inhibitors, have been used for the treatment of psoriasis." (PMID 35883888, 2022). "Most notably, TNF-α levels in injured tissues of patients with HS are even higher than those found in patients with psoriasis." (PMID 36359281, 2022). "Data for humoral immunogenicity in response to the second dose were missing for three patients with psoriasis; one each receiving a TNF inhibitor, IL-17 inhibitor, and IL-23 inhibitor." (PMID 34778846, 2022). "Normal human epidermal keratinocytes (NHEKs), HaCaT cells, and Ker-CT cells stimulated with M5 (IL-17A, IL-22, IL-1α, oncostatin M, and TNF-α) were used to establish a psoriasis model in vitro." (PMID 35586566, 2022). "The transcription factor activated by all three MAPK pathways, AP-1, is also important in the regulation of transcription of many molecules, including cytokines involved in psoriasis pathogenesis such as TNF-α and IL-6." (PMID 35883760, 2022). "The primary mechanism of action of TNF-α inhibitors in patients with psoriasis most likely involves the indirect inhibition of IL-17 signaling through the regulation of IL-23 production by myeloid DCs." (PMID 35884790, 2022). "MSCs-IT alleviated murine psoriasis-like inflammation by producing tumor necrosis factor (TNF) stimulating gene-6 (TSG-6), which inhibited neutrophil infiltration." (PMID 36433947, 2022).
psoriasis (continued). "Accumulating dermal iDC play a key role in the progression and sustenance of psoriasis by secreting large amounts of pro-inflammatory factors including iNOS, IL-23, and TNF-α." (PMID 35837394, 2022). "The expression of IL-17C is increased by TNF-α in keratinocytes and has been suggested as a epithelial biomarker in the onset of skin-inflammatory diseases, including psoriasis and AD." (PMID 36012541, 2022). "The inflammatory response of the body activates the secretion of TNF‐α by dendritic cells and induces a variety of secondary mediators and adhesion molecules related to psoriasis." (PMID 35174638, 2022). "In psoriasis patients, overproduction of multiple cytokines, for instance, TNF-α, IL-1, and IFN-γ, was expected to result in an increased expression of MMP-9." (PMID 35317170, 2022). "The tumor necrosis factor α (TNFα)–interleukin 23(IL‐23)‐IL17 axis is the basis of the pathophysiology of psoriasis." (PMID 35762118, 2022). "IFN-α and TNF-α released by pDC, macrophages, and other cells promote maturation and activation of myeloid DC, which play an important role in the chronic phase of psoriasis." (PMID 35837394, 2022). "Nicotine in tobacco smoke was the major alkaloid of cigarettes that activated the interleukin-1β (IL-1β), IL-2, IL-12, and tumor necrosis factor (TNF), which played a central role in psoriasis pathogenesis." (PMID 35646971, 2022). "In conclusion, we demonstrated that IRh improved IMQ-induced psoriasis-like dermatitis by decreasing TNF-α, IL-6, IL-17A, and nuclear NF-κB levels in the skin, and increasing malondialdehyde (MDA) levels in plasma." (PMID 36556472, 2022). "The mAbs for treating psoriasis are designed to block either the specific receptors or soluble mediators of the main pathways in the progress and chronicity of psoriasis, including TNF-α, IL-12/23, and IL-17." (PMID 35336028, 2022). "Other pharmacological agents commonly used in the treatment of psoriasis are TNF-alpha inhibitors, namely infliximab." (PMID 35204165, 2022). "The recent development in biologics blocking TNF-α, IL-12/23, and IL-17, which are key cytokines in psoriasis, contributes to promising outcomes for the treatment of psoriasis." (PMID 36450739, 2022). "This study did not identify two well-known cytokines that play an essential role in the pathogenesis of psoriasis and as drug targets (TNF-α and IL-17A)." (PMID 36483564, 2022). "Despite the efficacy of TNF-α inhibitors against psoriasis, the onset or worsening of psoriasis has been reported in patients treated with TNF-α inhibitors for various systemic inflammatory rheumatic diseases in numerous studies." (PMID 35884790, 2022). "Coptisine also lowered the levels of inflammatory cytokines TNF-α and IL-1β in the prefrontal cortex of psoriasis mice." (PMID 35209199, 2022). "Several mAbs designed to block either specific receptors or soluble mediators of the main pathways were approved for treating psoriasis, including TNF-α, IL-12/23, and IL-17 antibodies." (PMID 36052126, 2022). "In this study, we found that the expression of M1 markers (CD68 and iNOS) was enhanced in psoriasis mice and the pro‐inflammatory cytokines levels (TNF‐α, IL‐6, IL‐12, and IL‐23) were increased." (PMID 36444619, 2022). "Promising findings of a recent study demonstrated that Yangxue Jiedu Soup significantly decreased the secretion of Hsp70-containing exosomes in the plasma of psoriasis model mice by downregulating the production of TNF-α, IL-6, IL-1β, IFN-γ, IL-17, and IL-23." (PMID 36233237, 2022). "In patients with psoriasis, TNF-α, IL-12 family, and IL-17 cytokines were selected as the main therapeutic target of the new drugs." (PMID 35563587, 2022). "It was found in the skin lesions of psoriasis patients that TNF blockade with etanercept prevented TNF-mediated activation of myeloid dendritic cells, resulting in decreased IL-23 driven T-cell activation and a subsequent decrease in IL-17 levels in the skin." (PMID 35203534, 2022).